MIR217HG (MIR217 host gene)
Synonyms: MIR216AHG; MIR216BHG
Gene: Long non-coding RNA gene on chromosome 2 (55,963,191 to 56,049,708, reverse strand). Ensembl gene ENSG00000226702.
Gene Ontology:
Biological process: SRP-dependent cotranslational protein targeting to membrane, signal sequence recognition
Cellular component: signal recognition particle, endoplasmic reticulum targeting